BRAF (B-Raf proto-oncogene, serine/threonine kinase)
Diseases named in the same sentence as BRAF in open-access papers (continued):
Sharing a sentence is not in itself a finding about the gene and the disease.
thyroid cancer (continued). "In the setting of thyroid cancer, somatic BRAF V600E‐mutations are highly specific for PTC and can be analyzed in aspirates from fine‐needle aspiration cytology (FNAC)." (PMID 34156770, 2021). "In this study, 73 matched neoplastic tissue and plasma DNA samples and 54 plasma DNA samples from healthy individuals were examined for the diagnostic utility of ctDNA in thyroid cancers focusing on BRAF, KRAS, NRAS, and TERT promoter mutations." (PMID 33915745, 2021). "Six weeks after the administration of dabrafenib to patients with BRAF-mutated thyroid cancer, 6 of 10 patients had restored RAI uptake, 2 exhibited a partial response, and 4 had stable disease." (PMID 33995657, 2021). "Of 12 patients with increased radioiodine uptake, 5 out of 5 patients had NRAS-mutated thyroid cancer, while 4 of 9 patients had thyroid cancer with BRAF V600E mutation." (PMID 34944814, 2021). "BRAF mutation was the most prevalent (89%) in aggressive variants of PTC compared to that in other thyroid cancers." (PMID 33672707, 2021). "In this study, we investigated the molecular processes associated with drug response to BRAF inhibitors in BRAFV600E mutated thyroid cancer cell lines." (PMID 34072194, 2021). "BRAF V600E was the most common mutation in thyroid cancer, and it all occurred in Bethesda III or higher grade nodules which were categorized by TBSRTC." (PMID 34322384, 2021). "Overall, both mutational signature analysis in this study and earlier studies exhibited that mistranslation mutations of BRAF gene in thyroid carcinoma mutations play a pivotal role in thyroid carcinogenesis." (PMID 34697553, 2021). "BRAF V600E mutation has been characterized as highly specific for thyroid carcinoma, especially papillary thyroid carcinoma (PTC); human bone marrow endothelial marker-1 (HBME-1) and galectin-3 are also such markers that are highly specific for PTC." (PMID 34934597, 2021). "Recently, the RAS-RAF-MAP kinase signaling pathway has been implicated in many cancers, particularly more frequently in thyroid carcinomas, with the BRAF V600E mutation playing a vital role in papillary thyroid carcinoma." (PMID 34345541, 2021). "Numerous investigations mentioned high mutation rate of BRAF gene in various thyroid carcinomas, wherein T1799A nucleotide transversion is the most common oncogenic mutation of BRAF gene." (PMID 34697553, 2021). "Thyroid carcinomas express splicing variants of BRAF that lack the N-terminal auto-inhibitory domain, which results in constitutive BRAF activation and in turn activates the MAP kinase signaling pathway." (PMID 33923658, 2021). "In this study, we provide genetic characterization of locally advanced T4 well differentiated thyroid cancer and demonstrate that the majority (19/25, 76%) are driven by BRAF V600E mutation and 12 (48%) also harbor co-existent TERT promoter mutations." (PMID 32415114, 2020). "Here, we investigate if FOXE1 gene dosage is able to influence the outcome of experimental thyroid carcinoma in vivo by using a BRAF oncogene-induced thyroid cancer model with heterozygous Foxe1 knockout allele." (PMID 33375029, 2020). "A molecular test was devised using real-time PCR to detect common genetic alterations in thyroid cancer, including BRAF, N-, H-, and K-RAS mutations and rearrangements of RET/PTC and PAX8/PPARr." (PMID 32781560, 2020). "In thyroid cancer, the BRAF T1799A mutation is associated with aggressive pathological outcomes of PTC in which high platelet counts and increased PDGF production are observed." (PMID 32235327, 2020). "With the highest prevalence of BRAF V600E-associated thyroid cancer type in the world, a sole mutation test for BRAF V600E is commercially available for current clinical practice in Korea." (PMID 32781560, 2020).
thyroid cancer (continued). "Apart from the majority of BRAF-positive PTCs, the frequency of potentially targetable mutations in primary thyroid cancers are relative unexploited." (PMID 32265839, 2020). "Current diagnostic biomarkers in thyroid cancer include point mutations in the BRAF, NRAS, KRAS, HRAS genes, and rearrangements in paired box 8 (PAX8)/peroxisome proliferator-activated receptor gamma (PPARG) and RET." (PMID 33158279, 2020). "Concerning BRAF mutation in thyroid cancer, two reports have demonstrated that BRAF mutation promotes NHEJ activity through upregulation of NHEJ1 and it is also associated with radioresistance." (PMID 33195430, 2020). "BCPAP and KTC-1 thyroid cancer cell lines with the BRAF (V600E) mutation were used to examine the effects of increasing concentrations of MnTnBuOE-2-PyP on cell growth, using a clonogenic assay." (PMID 31728622, 2020). "BRAF mutation is the most frequent event in thyroid cancer, especially in PTC classic variant subtype." (PMID 33247684, 2020). "In Korea, as the BRAF V600E mutation is detected in 70–80% of thyroid cancer specimens, its testing in fine-needle aspiration (FNA) cytology specimens alone has been used for the differential diagnosis of thyroid nodules until now." (PMID 32781560, 2020). "To date, the most common alteration in thyroid cancer is BRAF gene mutation, which most often occurs in papillary (40–45%) and poorly differentiated cancers (20–40%) and whose prevalence in indeterminate lesions varies between 15% and 40%." (PMID 32351561, 2020). "The papillary histotype is the most frequent (over 80%) thyroid cancer histotype and is due to the oncogenic mutation of BRAF in most cases (over 50%)." (PMID 32408629, 2020). "A large body of evidence indicates that the frequency of BRAF mutations (almost exclusively occurring as exon 15 p.V600E; from 18% to 87%) varies among thyroid cancers." (PMID 33260892, 2020). "This is consistent with findings in other series of well differentiated thyroid cancer, where BRAF mutations in tumors>1 cm in size and particularly co-occurring BRAF and TERT mutations were associated with a significantly higher risk of disease recurrence." (PMID 32415114, 2020). "The MET pathway is insensitive to targeted drugs (e.g., BRAF or MEK inhibitors) in refractory thyroid cancer, which can cause a BRAFV600E mutation by activating the downstream PI3K/Akt pathway." (PMID 33489878, 2020). "There is a building body of evidence that co-mutations of BRAF/TERT signify a highly aggressive form of thyroid cancer that is more likely to recur." (PMID 32415114, 2020). "BRAF V600E mutation occurs more frequently in the advanced stages (stage III or IV) of thyroid cancer." (PMID 33520689, 2020). "The prevalence of mutations in indeterminate cytology was distinctively different from that of the entire population with the BRAF as the predominant driver mutation for thyroid cancer." (PMID 32781560, 2020). "The results of this study provide evidence that the majority of well differentiated T4 thyroid cancers have mutations in BRAF and/or TERT promoter regions." (PMID 32415114, 2020). "Our data show that COX-2 correlates with PTC disease-free survival in BRAF-mutated tumors, representing a useful prognostic marker for risk stratification of thyroid cancer patients." (PMID 33327467, 2020). "BRAF has been addressed as a prognostic marker in thyroid cancer in the literature, where associations were found with larger tumours, older age, miETE, and lymph node metastasis." (PMID 32659948, 2020). "To date, molecular testing has been widely studied for thyroid cancer with BRAF mutation as the most commonly used biomarker for preoperative diagnosis using FNAB specimens." (PMID 33247684, 2020). "High TUBB3 expression in thyroid cancer cells correlated with positivity to BRAF mutation-specific antibody." (PMID 33256003, 2020).
thyroid cancer (continued). "DN200434, the recently discovered orally bioavailable agonist of ESRRG, enhanced radioiodine therapy responsiveness in thyroid cancer with either KRAS or BRAF mutations both in vitro and in vivo." (PMID 32571331, 2020). "The major driver mutations of thyroid cancer include BRAF and RAS mutations, and transfusion/papillary thyroid carcinoma (RET/PTC) rearrangements." (PMID 32260561, 2020). "This fact can be at least partly explained by outstandingly high frequency of BRAF V600E mutation in the most frequent papillary subtype of thyroid cancer." (PMID 32111026, 2020). "BRAF V600E is the most commonly detected mutation in thyroid cancers and is specifically associated with papillary thyroid carcinoma." (PMID 32976686, 2020). "Since BRAFV600E is one of the most common mutations in PTC, BRAF inhibitors such as vemurafenib or dabrafenib have been implemented in the management of thyroid cancer." (PMID 32751138, 2020). "We further investigated the allele-specific expression of the mutant and wildtype alleles of the BRAF gene in the 13 thyroid cancer tissue samples with BRAFV600E mutation detected in both DNA and mRNA." (PMID 32357861, 2020). "Tandem oncogenic mutations in BRAF are also enriched in skin cancers relative to thyroid cancer, which also commonly involves oncogenic BRAF mutations." (PMID 33207206, 2020). "The BRAF mutation present in the two successfully reprogramed ATCs can be found in ∼55% of advanced thyroid cancers, most commonly a valine-to-glutamic acid substitution at residue 600 (p.V600E)." (PMID 32795421, 2020). "Nevertheless, the current study identified the highest BRAF V600E mutation rate in ages around 30 years, suggesting an earlier onset age of thyroid cancer in Chinese women." (PMID 32671901, 2020). "There have been reports about the efficacy of vemurafenib in thyroid cancer, hairy cell leukemia, and lung cancer with BRAF mutations." (PMID 32476297, 2020). "In thyroid carcinoma, RNA-Seq analysis has identified that 560 genes are differentially expressed in BRAF V600E-mutated tumors compared to BRAF wild-type tumors." (PMID 33198372, 2020). "In the case of thyroid carcinomas arising from the follicle cells, the mutation of the BRAF and RAS genes are the most common; the BRAF gene mutation was considered present especially in papillary thyroid carcinomas." (PMID 32575591, 2020). "Dabrafenib is a potent BRAF inhibitor and in addition we detected BRAF mutations as a sensitivity marker in thyroid carcinoma." (PMID 33274713, 2020). "In the ectoderm group, The BRAF V600E missense mutation with the highest incidence was mainly presented in 288 cases with thyroid carcinoma and 206 cases with skin cutaneous melanoma." (PMID 33308219, 2020). "The combination testing correctly diagnosed 27 out of 39 thyroid carcinomas, including 2 benign and 3 indeterminate cases in cytology which have BRAF mutation-positive." (PMID 33247684, 2020). "From a prognostic perspective, BRAF-mutated thyroid carcinomas feature more aggressive behavior and poorer outcomes than wild-types." (PMID 33260892, 2020). "The BRAF mutation is associated with the oncogenesis of several tumors as well as colon cancer, melanoma and thyroid cancer." (PMID 32575591, 2020). "A meta-analysis of 27 studies (n = 5655) suggests the association between BRAF p.V600E mutated thyroid cancer and extrathyroidal extension, lymph node metastasis, more advanced stage." (PMID 31835496, 2019). "Patients with solitary intrathyroidal BRAF p.V600E mutated thyroid cancer are at a higher risk for recurrence." (PMID 31835496, 2019). "This pathway, especially BRAF mutations, is considered a potential therapeutic target for thyroid cancer treatment." (PMID 32351906, 2019).
thyroid cancer (continued). "Recently, a genome expression profile analysis of infiltrating immune cells in the microenvironment the BRAF-mutated thyroid cancers showed an over-expression of a panel of genes involved in local immunosuppression processes." (PMID 31762942, 2019). "Given that above well-characterized role of BRAF mutations prompted us to explore the functions of low dose of ionizing radiation (LDR) in BRAF-mediated cellular transformation in thyroid cancer cells." (PMID 30760304, 2019). "The BRAF gene mutation and the RET/PTC rearrangement show a reciprocal age-association, and in fact, the prevalence of the BRAF mutation in childhood thyroid cancers after the Chernobyl accident is below 10% on average." (PMID 31480712, 2019). "TERT, a predominant determinant for controlling the activity of telomerase, was likely to coexist with BRAF V600E mutation in thyroid cancer." (PMID 31300059, 2019). "BRAF V600E mutation was correlated with more aggressive and iodine-resistant phenotypes, providing valuable prognostic information for thyroid cancer." (PMID 31300059, 2019). "Although BRAF p.V600E is the most common mutation in thyroid cancer, the association between activating mutations and the metabolic reprogramming has not been clearly demonstrated." (PMID 31835496, 2019). "In early 2003, BRAF mutations were reported in thyroid cancer with an occurrence ranging from 25 to 42%." (PMID 30760304, 2019). "The study using the next-generation sequencing platform for targeted sequencing of selected 341 genes (MSK-IMPACT) in 84 samples of PDTC showed somatic mutations commonly seen in differentiated thyroid cancer such as BRAF p.V600E (33%) and RAS (28%)." (PMID 31835496, 2019). "In thyroid tumors, the circulating BRAF mutation is now taken into account for both thyroid cancer diagnosis and determination of the most effective treatment strategy." (PMID 32351906, 2019). "Individuals born before the accident are now at least thirty-three years old, and recent reports demonstrate that the frequency of thyroid cancer driven by the BRAF mutation tends to grow in the affected group." (PMID 31480712, 2019). "Recently activating somatic mutations in the BRAF proto-oncogene has been discovered in various malignancies, such as in melanoma (60–70% of cases), colon cancer (10%) including thyroid cancer (35–70%)." (PMID 30760304, 2019). "In particular, among thyroid cancer cells harboring different oncogenic mutations, those bearing the BRAF V600E mutation secrete the highest amounts of CXCL8." (PMID 31762942, 2019). "From 29 studies reporting on BRAF mutations in more than 2,000 examined thyroid cancers, the average frequency of mutations in PTC was 44% and in anaplastic thyroid cancer (ATC) was 24%." (PMID 31810221, 2019). "It has been demonstrated that clinical prognosis is significantly worse when the BRAF mutation is present along with a TERT mutation, complicating the role that BRAF has in thyroid cancer." (PMID 31443155, 2019). "Since BRAFV600E accounts for > 85% of BRAF mutations in thyroid carcinomas we evaluated the BRAFV600E expression in human thyroid cancer cells." (PMID 30760304, 2019). "Initiating mutations or gene fusions in the thyroid carcinoma include: BRAF in PTC, N-K-H-RAS in PTC and/or follicular thyroid carcinoma (FTC), RET/PTC in PTC, and PAX8/PPARγ in FTC." (PMID 31717363, 2019). "BRAF exon 15 V600 mutation analysis was performed in 185 thyroid carcinomas out of which mutations were detected in 89 cases (48.1%)." (PMID 30666518, 2019). "Recently, promoter mutations in the telomerase reverse transcriptase encoding gene (TERT) have been consistently associated with more aggressive thyroid carcinomas, especially in the presence of BRAF mutation." (PMID 30884810, 2019).
thyroid cancer (continued). "Some tumors are characterized by the prevalence of a mutation in a specific gene, such as the G-protein coding BRAF in thyroid carcinoma or IDH1, translating into isocitrate dehydrogenase, in low-grade glioma." (PMID 31379928, 2019). "A trans-version from thymine to adenine (T1799A), leading to a Glu for Val substitution at residue 600 (V600E), accounts for > 92% of BRAF mutations in thyroid carcinomas." (PMID 30760304, 2019). "Molecular genetic analyses revealed several frequent DNA anomalies in thyroid cancer, including the mutations of BRAF, NRAS and RET/PTC genes, the prognostic significance of which is still debated in the individual subcategories of thyroid carcinoma." (PMID 30666518, 2019). "The BRAF gene mutation was detected in the PTCs of two of the three patients who had been diagnosed with thyroid cancer." (PMID 29593792, 2018). "The most common mutation associated with thyroid cancer involves BRAF codon V600, followed by mutations in RAS." (PMID 30249281, 2018). "Our analysis also uncovered that BRAF V600E mutation in thyroid cancer (THCA) creates an immune suppressive tumor microenvironment by increasing Treg, neutrophil, and monocyte infiltration, while decreasing the infiltration of NK cells and CD4+ T-cells." (PMID 30622534, 2018). "In thyroid cancer, point mutations in Ras and BRAF genes, as well as rearrangements of the RET gene (RET/PTC), lead to the constitutive activation of MAPK pathways that initiate and/or sustain thyroid tumorigenesis." (PMID 29467389, 2018). "NIS is negatively regulated by the MAPK pathway in thyroid cancer, in which the BRAF V600E mutation plays an important role." (PMID 30337961, 2018). "Incorporating these findings, recent American and European guidelines support the use of mutation testing of genes associated with thyroid cancer (BRAF, RAS, RET/PTC, PAX8/PPARG) in order to improve surgical decision making." (PMID 30249281, 2018). "Blood tumors were largely defined by the scarcity of point mutations, and skin cutaneous melanoma and thyroid cancer were clustered together based on a high frequency of the BRAF hotspot mutation." (PMID 29572294, 2018). "To test this, we chose thyroid cancer cell lines containing mutations in the commonly mutated oncogenes; BRAF, RAS, and PIK3CA, along with two cell lines sensitive to dasatinib; the BRAF mutant, BCPAP, and the RAS-mutant, Cal6210." (PMID 29487290, 2018). "Almost all thyroid cancer samples belong to cluster V, along with samples from other cancer types, and this cluster exhibits a strong enrichment in BRAF mutations (17% compared to an overall rate of 7%)." (PMID 30341300, 2018). "The BRAF p.V600E mutation was most frequent in skin cutaneous melanoma and thyroid carcinoma, affecting 43% (n = 193) and 56% (n = 29) of samples respectively." (PMID 30412573, 2018). "Molecular analysis typically involves a BRAF (V600E) mutation, which has emerged as a marker of aggressive behavior in thyroid cancer and is associated with clinical progression and recurrence of PTC." (PMID 28009980, 2017). "The most common and well recognized genetic alteration in thyroid cancer is BRAF(V600E) mutation, which is present in up to 45% of thyroid malignancies and in up to 62% of radioactive iodine-resistant thyroid tumors." (PMID 28117293, 2017). "The constitutively active BRAF V600E protein has been associated with worse clinical outcomes in thyroid cancer." (PMID 28974264, 2017). "Common genetic alterations found in thyroid cancer include point mutation of the BRAF and RAS genes (seen up to 45% of patients) as well as RET/PTC and PAX8/PPARγ chromosomal rearrangements." (PMID 28117293, 2017). "RAS (HRAS and NRAS) mutations are the second most common genetic alterations in thyroid cancers, which were mutually exclusive with BRAF mutations (the most common mutations in thyroid cancers)." (PMID 28582771, 2017).